TGFB2 (transforming growth factor beta 2)
Diseases named in the same sentence as TGFB2 in open-access papers (continued):
Sharing a sentence is not in itself a finding about the gene and the disease.
cataract (13 papers, 2011 to 2024). Partial or complete opacity of the crystalline lens of one or both eyes that decreases visual acuity and eventually results in blindness. "In cataract patients, the AH level of bioactive TGFβ2 was similar to many previously reported values." (PMID 31382918, 2019). "In the present study, real-time quantitative reverse transcription (QRT)-PCR was applied to investigate the changes in TGFβ1, TGFβ2, and TGFβ3 gene expression in fragments of ALCs and PBMCs from pediatric patients with congenital and traumatic cataracts." (PMID 22128246, 2011). "For traumatic cataracts, a positive correlation was only observed between the expression of TGFβ1 and TGFβ2 in ALCs, whereas for PBMCs, a positive correlation was only affirmed between the expression of TGFβ1 and TGFβ3." (PMID 22128246, 2011). "Significant differences were found for TGFβ1 and TGFβ2 expression profiles in PBMCs between the patients with congenital and traumatic cataracts." (PMID 22128246, 2011). "In PBMCs, the expression of TGFβ1 and TGFβ2 was about twofold higher in the congenital cataract patients compared to the patients with traumatic cataracts, and a statistical significance was found (TGFβ1 p<0.0001, TGFβ2 p<0.0001, Mann–Whitney U test)." (PMID 22128246, 2011). "Likewise, our results revealed higher mRNA levels of TGFβ1 and TGFβ2 in ALCs of traumatic cataract patients." (PMID 22128246, 2011). "Overexpression of TGFβ1 and TGFβ2 in the PBMCs of patients with congenital cataracts might indicate that these cytokines are involved in the development of lens opacity." (PMID 22128246, 2011). "Overexpression of TGFβ1 and TGFβ2 in the PBMCs of patients with congenital cataracts might indicate the involvement of these cytokines in the development of lens opacity." (PMID 22128246, 2011). "Interestingly, the subjects with congenital cataracts showed a significant elevation of TGFβ1 and TGFβ2 expression in PBMCs when compared to those with traumatic cataracts, which suggests that traumatic cataractogenesis is mediated differently from congenital cataractogenesis." (PMID 22128246, 2011). "To further certify the involvement of PYK2 in fibrotic cataracts, we knocked down the PYK2 by siRNA and found that the knockdown of PYK2 can allay the TGFβ2-induced EMT by suppressing the phosphorylation of ERK, JNK, P38, and AKT." (PMID 39333897, 2024). "TGFβ1, TGFβ2, and TGFβ3 isoforms were detected in ALC and PBMC samples obtained from patients with congenital and traumatic cataracts." (PMID 22128246, 2011). "In ALCs, there was no significantly different expressions of TGFβ1, TGFβ2, and TGFβ3 between congenital and traumatic cataracts (TGFβ1 p=0.78, TGFβ2 p=0.75, TGFβ3 p=0.23, Mann–Whitney U test)." (PMID 22128246, 2011).
lung fibrosis (13 papers, 2011 to 2026). "Further, inhibiting both TGFβ2 and TGFβ3 while sparing TGFβ1 could alleviate lung fibrosis while avoiding toxicity concerns associated with pan-TGFβ blockade." (PMID 34785671, 2021). "Therefore, DPP4 deficiency in those cell types might relate to the low expression levels of Tgfb1 and Tgfb2 in the lungs with BLM‐induced pulmonary fibrosis." (PMID 36949656, 2023). "In our study, the downregulation of the expression levels of Tgfb1 and Tgfb2 in the lungs was demonstrated, suggesting a central mechanism to ameliorate BLM‐induced pulmonary fibrosis." (PMID 36949656, 2023).
allergic disease (11 papers, 2015 to 2025). An immune response that occurs following re-exposure to an innocuous antigen, and that requires the presence of existing antibodies against that antigen. "The results support the concept that IL13 and HGF have protective effects and TGFβ2 may act as a risk factor, which may explain the diversity of results from epidemiological studies on the health-promoting effects of breastfeeding with regards to allergic diseases." (PMID 28538696, 2017).
head and neck squamous cell carcinoma (10 papers, 2016 to 2025). A squamous cell carcinoma that arises from any of the following anatomic sites: lip and oral cavity, nasal cavity, paranasal sinuses, pharynx, larynx, and salivary glands. "TGFβ2 stimulation reduces ERK1/2 and increases p38 activity, thereby suppressing metastasis in human head and neck squamous cell carcinoma (HNSCC) cells." (PMID 32168915, 2020).
aortic aneurysm (9 papers, 2015 to 2023). A ruptured aneurysm located in the wall of the proximal portion of the descending aorta proceeding from the arch of the aorta. "Among the three TGFβ ligands, TGFB2 mutations which cause Loeys–Dietz syndrome 4 (LDS type 4) have been linked to aortic aneurysm and rupture and congenital heart defects, including valve malformations and septation abnormalities." (PMID 33801433, 2021). "These suggestions are consistent with the clinical findings indicating the presence of aortic and mitral valve diseases and aortic aneurysm in the LDS patients with genetic mutations in TGFB2 (LDS4) or TGFB3 (LDS5)." (PMID 32456345, 2020). "Mutations affecting similar amino acids in TGFB2 have been shown to be causal in syndromic forms of aortic aneurysms." (PMID 25835445, 2015). "Moreover, haploinsufficiency in TGFB2 causes thoracic aortic aneurysms and we replicate this result by observing an association between aortic aneurysm risk and rs192335285-T (OR = 2.53 [1.43–4.45], P = 1.3 × 10−3; 2825 cases)." (PMID 36653477, 2023). "Fbn1C1039G/+:Tgfb2+/− mice rapidly developed aortic aneurysms." (PMID 30037098, 2018).
cardiac hypertrophy (9 papers, 2013 to 2025). "Data also showed up-regulation of about 180 genes including Tgfb2, Ace, Atf3, Ctgf, Angpt14, Col9a2, Wisp2, Nppa, Nppb, and Actn1 that are linked to cardiac muscle contraction, cardiac hypertrophy, cardiac fibrosis and myocardial injury." (PMID 27548259, 2016). "Edn3 and Tgfb2, encoding Endothelin 3 and TGF-β2, respectively, may induce cardiac hypertrophy, whereas GDF15 induces cellular senescence and inflammation." (PMID 39119147, 2024). "In a murine model of cardiac hypertrophy, a pathology that involves fibrosis, Sox9, Tgfb2, and Tgfb3 were mutually upregulated and predicted to interact; however, this was not experimentally confirmed or linked to ECM regulation." (PMID 37510994, 2023). "Consistently, B38-CAP treatment significantly downregulated increased expression of mRNA associated with the pathology of cardiac hypertrophy (BNP and β-myhc) and fibrosis (Col8a1, Postn, and Tgfb2)." (PMID 32103002, 2020). "In addition, the attenuation of Tgfb2 expression presumably contributed to the decreased myocardial hypertrophy and fibrosis in AAV9sc.PBD-treated TM54 mice." (PMID 38572067, 2024). "Thus, we verified the expression of the fetal phenotype and atrophy-related marker Tgfb2 and the markers of cardiac hypertrophy Egr1 and Ccna2." (PMID 37108224, 2023). "Our results confirm previous work in rodent models of hypoxia, with respect to expression of fetal genes (NPPA, NPPB), fibrotic genes (TGFB2, CTGF, LTBT2), and genes marking cardiac hypertrophy (NPPB, THBS4) in the heart after exposure to hypoxia." (PMID 31960631, 2020).
Hypertension (9 papers, 2016 to 2025). The presence of chronic increased pressure in the systemic arterial system. "According to RGD annotations, there were several genes related to CNS diseases (Abcg2, Ephx2, RGD1563482, Tgfb2, Mal, and Cst3), and 3 genes associated with hypertension (Ephx2, Cst3, and Ltbp2) are found on this list." (PMID 26822062, 2016). "Active TGF-β binding to TGFβ2 on the cell membrane activates TGFβR1, initiating the TGFβ signaling pathway and regulating cell hypertension, proliferation, apoptosis, differentiation, and morphogenesis." (PMID 35562675, 2022). "This predicted activation was accompanied by transcriptional up‐regulation of TGFβ1 and TGFβ2 upon DS‐induced hypertension." (PMID 31368189, 2019).
liver cancer (9 papers, 2014 to 2024). An epithelial or non-epithelial malignant neoplasm that arises from the liver. "GM-CSF recruits p-SHP-2 for dephosphorylation by up-regulating HoxA10HOXA10 activates the transcription of TGFβ2 by interacting with tandem cis-elements in the promoter thereby regulating the proliferation and migration of liver cancer cells." (PMID 38644382, 2024). "In addition, GM-CSF also promoted the expression of p-HOXA10 and TGFβ2 in liver cancer cells and inhibited the inhibitory effect of SHP-1." (PMID 38644382, 2024). "Moreover, we found that PMEPA1 mRNA expression is upregulated in human HCC samples, and its level correlates with TGFβ1, TGFβ2, and TGFβ3 mRNA expression in TCGA liver cancer samples." (PMID 33608500, 2021). "To further study the mechanism of SHP-1 inhibition of liver cancer, we analyzed the expression of p-HOXA10/TGFβ2 in macrophage and the migration ability of SMMC7721 cells under the interference of GM-CSF and hypoxia." (PMID 38644382, 2024). "In the liver cancer (LIHC), the well-predicted genes are RB1 and TGFβ2." (PMID 34556802, 2021). "Moreover, expression of TGFB2, but not TGFB1 was increased by BTC in vitro, repressed by DHA in both prevention and treatment mouse studies, and increased in human liver cancer meta‐analysis." (PMID 37859621, 2023).
lung adenocarcinoma (9 papers, 2018 to 2025). A carcinoma that arises from the lung and is characterized by the presence of malignant glandular epithelial cells. "Further evidence for TGFB2 versatility is that 2 TGFB2 ligand mutations Cys246Tyr and Cys407Ser share a lung adenocarcinoma phenotype with a mutation in β8Cys@1 of INHBA Cys244Tyr." (PMID 36214621, 2022). "Our research demonstrates that CCNA2 and TGFB2 are potential diagnostic and prognostic biomarkers, as well as therapeutic targets in lung adenocarcinoma (LUAD)." (PMID 33195410, 2020). "Correlation analysis using RNA sequencing data from the TCGA further showed that TGFB2 correlated significantly with EPHA2 expression in lung adenocarcinoma samples, though other myeloid markers and immunosuppressive proteins were not significantly correlated with EPHA2 expression." (PMID 40867322, 2025). "In order to find supporting evidence in clinical samples for our model, we searched the expression data for GATA4, TGFB2, and WNT7B in lung adenocarcinoma patients from The Cancer Genome Atlas (TCGA)." (PMID 30971692, 2019).
malignant glioma (9 papers, 2014 to 2025). A grade III or grade IV glioma arising from the central nervous system. "Previous studies have reported that there was elevated expression of TGFβ1 and TGFβ2 in both blood serum and tumor tissues of patients with malignant glioma." (PMID 32974124, 2020). "Considering these results, the preset study hypothesized that the ability to resist TGFβ2-mediated growth inhibition in malignant glioma cells was due to a decrease in the expression levels of Smad2 and Smad3 in the TGFβ2 signaling pathway." (PMID 25891822, 2015). "The transforming growth factor beta-2 (TGF-β2), a polypeptide cytokine found to be specifically overexpressed in malignant gliomas, plays a crucial role in the malignancy and progression of the tumor." (PMID 37242677, 2023). "In contrast, some other studies suggest that constitutive AhR activity positively controls TGFβ1, TGFβ2, and LTBP-1 in malignant glioma cells." (PMID 24795504, 2014).
Myocardial fibrosis (9 papers, 2013 to 2025). "This was further confirmed in qRT–PCR measurement of gene expression changes of Ctgf as well as Tgfβ2, another key regulator of myocardial fibrosis." (PMID 39196168, 2022). "In the animal model, epirubicin-induced circumferential strain (CS) decrease correlates with myocardial fibrosis assessed histologically and by a significant increase in COL1 and TGFB2 expression." (PMID 39857629, 2024). "Finally, we observed a strong correlation between the decrease in left ventricular CS with myocardial fibrosis assessed histologically (r = 0.899, p = 0.002) and with the expression of COL1 (r = 0.739, p = 0.036) and TGFB2 (r = 0.9, p = 0.002)." (PMID 39857629, 2024).
non-small cell lung carcinoma (9 papers, 2017 to 2025). A group of at least three distinct histological types of lung cancer, including non-small cell squamous cell carcinoma, adenocarcinoma, and large cell carcinoma. "Recently, regulation of TGFβ2 by miR-7 was reported in a non-small cell carcinoma cell line cultured under acidic conditions." (PMID 39992949, 2025). "For example, TGFB2 can mediate epithelial-mesenchymal transition and NF-κB pathway activation, thereby conferring resistance to osimertinib in non-small cell lung cancer." (PMID 38914663, 2024). "For instance, TGFB2 induced epithelial-mesenchymal transition and activated the NF-κB pathway to contribute to osimertinib resistance in epidermal growth factor receptor (EGFR) mutant non-small cell lung cancer." (PMID 38914663, 2024).
thoracic aortic aneurysm (9 papers, 2014 to 2024). An aneurysm formed in the wall of the proximal portion of the descending aorta proceeding from the arch of the aorta. "Indeed, pathogenic variants or deficiency of TGF-β pathway genes, including TGFB2, TGFB3, TGFBR1, TGFBR2, and SMAD3, confer risks for aortic destruction and thoracic aortic aneurysm formation." (PMID 38916960, 2024).
diabetic retinopathy (8 papers, 2013 to 2025). "In retinal vascular diseases such as diabetic retinopathy and age-related macular degeneration, TGFβ2, CD9, and CTGF are elevated, inducing choroidal and retinal micro vessel development." (PMID 35456925, 2022). "And we found TGFβ2, which was upregulated in cone dramatically by hyperglycemia, inhibited microglia activation at the early stage of diabetic retinopathy." (PMID 34434927, 2021). "Human retinal pericytes (HRP) have also been used to test the effects of TGFβ1 and TGFβ2 in the induction of BIGH3 protein and apoptosis, suggesting that the increase of the BIGH3 causes loss of retinal pericytes during early events in diabetic retinopathy." (PMID 35072165, 2021).
lymph node metastasis (8 papers, 2010 to 2024). "Expression level of TGFβ2 was found to be associated with lymph node metastasis and overall survival of the patients with ESCC." (PMID 32832354, 2020). "Moreover, high TGFβ2 expression was significantly associated with lymph node metastasis (Pearson χ2 test, P < 0.001)." (PMID 32832354, 2020). "This elevated TGFβ2 expression was also a reliable predictor of the presence of lymph node metastasis in GC patients, indicating that TGFβ2 may be a valuable prognostic indicator of metastatic progression in GC tumour types." (PMID 32530106, 2020). "The scores of SRGN staining positively correlated with the scores of TGFβ2 staining in TNBC tissues, and was significantly higher in TNBC tissues with lymph node metastasis (Nodal Positive) than in TNBC tissues without lymph node metastasis (Nodal Free)." (PMID 28692037, 2017).
aneurysm (7 papers, 2015 to 2025). Bulging or ballooning in an area of an artery secondary to arterial wall weakening. "We identified only one patient with a TGFB2 pathogenic variant, whose cardiovascular features consisted in mitral valve prolapse and insufficiency, mild arterial tortuosity and varicose veins, in the absence of aneurysms." (PMID 31569402, 2019).
cervical cancer (7 papers, 2008 to 2025). A primary or metastatic malignant neoplasm involving the cervix. "In hematologic malignancies cervical cancer and multiple myeloma SOX6 demonstrates tumor-suppressive properties by inhibiting proliferation, inducing cellular senescence or apoptosis, and regulating critical pathways including TGFβ2-Smad2/3 and LIN28B-MYC." (PMID 40866912, 2025).
colitis (7 papers, 2011 to 2025). Inflammation of the colon. "Furthermore, the mRNA level of TGFB1 was up-regulated much higher than that of TGFB2 and TGFB3 in hUC-MSCs stimulated by MLNs homogenates from colitis mice." (PMID 38956621, 2024).
mesothelioma (7 papers, 2012 to 2022). A usually malignant and aggressive neoplasm of the mesothelium which is often associated with exposure to asbestos. "On the other hand, when given to mesothelioma cells, TGFβ2 delayed the nuclear transport of syndecan-1 in parallel with an antiproliferative effect." (PMID 23144729, 2012). "Therefore, we analyzed the mRNA expression levels of INHBA (activin-A subunit), TGFB1 and TGFB2 in mesothelioma cells." (PMID 29228689, 2017).
Obesity (7 papers, 2013 to 2024). Accumulation of substantial excess body fat. "After adjusting for obesity, comorbidities, age, smoking, alcohol consumption, and ethnicity, our model predicted 66% and 48% increases of TGFβ1 and TGFβ2 by T2D, respectively, in this cohort of AA and LA." (PMID 38541912, 2024). "We exemplify this by identifying a putative long range cis regulatory mechanism at the LYPLAL1/TGFB2 obesity locus." (PMID 35746833, 2022). "Among them, the upregulated gene BCL2A1 is common in CVD, HTN, obesity, and aging; RNF144B and PTGIS are common in HCL, obesity, aging, and CVD; G0S2, CXCL1, ACKR3, and PTPRD are found in HTN, aging, and CVD; TGFB2, CA12, and MSR1 are familiar in obesity, aging, and CVD." (PMID 36035865, 2022).
renal cell carcinoma (7 papers, 2015 to 2023). "In renal cell carcinoma, knockdown of TGFB2 inhibited cell proliferation, migration, and invasion." (PMID 34299042, 2021). "In renal cell carcinoma cell lines miR-145-5p is dysregulated and several targets, including e2F-associated phosphoprotein (EAPP), Heparan Sulfate 6-O-Sulfotransferase 2 (HS6ST2), Lysyl Oxidase (LOX), Transforming Growth Factor beta-2 (TGFB2) and Vaccinia-related Kinase 2 (VRK2), were confirmed." (PMID 30102719, 2018).
brain tumor (6 papers, 2017 to 2023). "Among them, TGFβ1 and TGFβ2 are involved in brain tumor development and progression, particularly in high-grade GBM." (PMID 29132376, 2017). "A quantitative assessment of TGFβ2 mRNA in patients suffering from brain tumors may facilitate the identification of the stage of the lesion and be a potential method to complement the diagnostic process." (PMID 35454784, 2022). "In addition, TGFβ2 is a TGFβ family member that has been found to be specifically involved in brain tumor development and progression." (PMID 29110682, 2017).
endometriosis (6 papers, 2014 to 2026). The growth of functional endometrial tissue in anatomic sites outside the uterine body. "Interestingly, endometriosis-associated gene dysregulation in early secretory phase matches dysregulation in the transgenic mouse endometrium in the present study in terms of affected gene-set, above all the progesterone-regulated genes (e.g. Errfi1, Bcl6, Cited2, Irs2, Tgfb2, Gpx3, Tk1)." (PMID 38346980, 2024). "Increased expression of TGFB2 was found in ectopic lesions of women with endometriosis, and in rat models, high levels of TGFB2 were associated with more advanced stages of the disease." (PMID 38203610, 2023). "Therefore, in endometriosis stroma cells, the MLLT11 regulates TGFB2 and ACTA2 expression independently, and TGFB2 signaling does not seem to be involved in the regulation of ACTA2." (PMID 38203610, 2023).
mitral valve disease (6 papers, 2014 to 2024). "Heterozygous mutations in TGFB2 results congenital heart defects and adult aortic valve malformation and mitral valve disease or mitral valve prolapse." (PMID 33801433, 2021). "Heterozygous mutations in TGFB2 in patients of connective tissue disorders result in congenital heart defects and adult valve malformations, including mitral valve prolapse (MVP) with or without regurgitation." (PMID 33801433, 2021).